IL1B (interleukin 1 beta)
Diseases named in the same sentence as IL1B in open-access papers (continued):
Sharing a sentence is not in itself a finding about the gene and the disease.
diabetic retinopathy (68 papers, 2007 to 2025). "Interleukin-1β (IL-1β) has emerged as one of the most prominent pro-inflammatory cytokines associated with diabetic retinopathy." (PMID 39483336, 2024). "On the one hand, IL1β is linked to various eye diseases such as diabetic retinopathy and retinal detachment." (PMID 35883547, 2022). "The cytokine IL-1β is increased in the vitreous of patients with diabetic retinopathy and has been implicated in disease progression." (PMID 30057551, 2018). "Finally, another potential limitation is the absence of an association between secondary complications, such as diabetic retinopathy, and the IL-1β levels." (PMID 35268394, 2022). "Additionally, the expression of IL1B is upregulated in the diabetic retina and has been implicated in the pathogenesis of diabetic retinopathy." (PMID 33164750, 2020). "IL-1β, crucial in modulating insulin secretion and β-cell apoptosis, increases significantly with diabetic retinopathy severity." (PMID 41030257, 2025). "We conclude that any intervention in caspase-1/IL-1β/IL-1R1 feedback signaling presents novel therapeutic options for the treatment of diabetic retinopathy." (PMID 39483336, 2024). "Increased levels of proinflammatory cytokines such as tumor necrosis factor-alpha (TNF-α), interleukin-1 beta (IL-1β), and interleukin-6 (IL-6) have been detected in the vitreous and retina of people with diabetic retinopathy." (PMID 38918766, 2024). "Several studies report a role for GAL-1 in diabetic retinopathy, and it is possible that our observation is indicative of a shared regulation for IL-1β and IL-8 and GAL-1 in the microvascular pathophysiology of T1D." (PMID 38088456, 2024). "A comparative analysis between humans and rodents indicates that proinflammatory factors such as TNF-α, IL-1β and IL-6 are correlated with diabetic retinopathy." (PMID 37670018, 2023). "IL1β induces pericyte apoptosis through NF-κB activation under high glucose conditions, thereby increasing endothelial permeability in diabetic retinopathy." (PMID 36686646, 2022). "The results showed that these genes were enriched in inflammasome complex, interleukin-1 beta production, and other pathways, confirming the role of pyroptosis in diabetic retinopathy." (PMID 35957838, 2022). "For example, patients with diabetic retinopathy show increased levels of IL1β and TNFα in vitreous humor and serum." (PMID 35883547, 2022). "It was demonstrated that IL-1β increased in the diabetic mouse retina and IL-1β induced pericyte apoptosis via NF-κB activation under high glucose conditions, thereby increasing endothelial permeability in diabetic retinopathy." (PMID 35268394, 2022). "Proinflammatory cytokines that contribute to pathogenesis of diabetic retinopathy such as vascular leakage, endothelial cell apoptosis and capillary degeneration including IL‐6, IL‐1β, IL‐17A, MCP‐1, and TNFα." (PMID 34319011, 2021). "In the retina, IL1β has been shown to promote retinal neuroinflammation and drive neurodegeneration, for example, in photoreceptor degeneration, diabetic retinopathy, and age-related macular degeneration." (PMID 34776838, 2021). "Recent findings show that the prostaglandin E2 and its cognate EP2 receptor plays role in inducing the expression of not only IL1β but also the inflammasome NLR family pyrin domain containing 3 (NLRP3) signaling in diabetic retinopathy." (PMID 34319011, 2021). "IL-1β, a pivotal inflammatory cytokine, plays a critical role in the pathogenesis of diabetic retinopathy." (PMID 35010703, 2021). "By inhibiting the activation of NLRP3, ASC, caspase-1, and NF-κB to reduce the production of IL-1β and IL-18, propelling RvD1 to be expected an effective means to alleviate the progression of diabetic retinopathy." (PMID 33967796, 2021). "Minocycline is one of the tetracycline antibiotics, and it reduces the inflammatory cytokines, including IL-1β, by inhibiting microglia activation in diabetic retinopathy." (PMID 35010703, 2021).
diabetic retinopathy (continued). "Some traditional pro-inflammatory factors, such as C-reactive protein (CRP) and IL-1β, is being identified as the novel therapeutic targets of diabetic retinopathy." (PMID 33213461, 2020). "Recently, in another independent longitudinal survey of diabetic patients, the authors identified that IL-1β had a positive relationship with the development of diabetic retinopathy." (PMID 33213461, 2020). "For instance, the Justification for the Use of Statins in Primary Prevention: an Intervention Trial Evaluating Rosuvastatin (JUPITER) trial found that higher serum levels of CRP and IL-1β were correlated with diabetic retinopathy." (PMID 33213461, 2020). "In diabetic retinopathy, there is an increase of pro-inflammatory cytokines and chemokines like monocyte chemoattractant protein 1, TNFα, interleukin 1β (IL-1β) and IL-6." (PMID 31739614, 2019). "One article suggested that IL-1β accelerates apoptosis of retinal capillary cells, which play part in development of diabetic retinopathy." (PMID 31513661, 2019). "In diabetic retinopathy, a study showed that inhibition of autophagy in retinal pigment epithelial cells induced IL-1β release via ROS mediated NLRP3 inflammasome activation under high glucose condition." (PMID 30692509, 2019). "In fact, hyperglycemia triggers the increase in IL-1β production in diabetic retinopathy that is mainly produced by retinal vascular endothelial cells." (PMID 30057551, 2018). "Although an increase in retinal IL-1β levels has been described in diabetic conditions and correlated with the pathogenesis of diabetic retinopathy, it is still unclear which retinal cells express IL-1β and IL-1RI." (PMID 28588350, 2017). "Taking into account that IL-1RI is a crucial locus of control of IL-1β activity, blocking IL-1RI activity should be considered as a possible therapeutic strategy for the treatment of diabetic retinopathy." (PMID 28588350, 2017). "Beyond the early glycemia-driven stages of diabetic retinopathy, the propagation of inflammatory mediators such as Interleukin 1-beta (Il1b), monocyte chemotactic protein-1 (MCP-1) and adhesion molecules are upregulated and can contribute to capillary damage." (PMID 27942008, 2016). "Proinflammatory cytokines, as TNF and IL-1β, were found to be increased in the vitreous of patients with diabetic retinopathy, as well as IL-6." (PMID 25873768, 2015). "It was found that inflammatory mediators such as TNF-α and IL-1β contribute to the pathogenesis of diabetic retinopathy and significantly higher levels of these markers were found in diabetic vs. healthy control subjects." (PMID 26262605, 2015). "The inflammatory profile of diabetic retinopathy has been confirmed in animal models of diabetes, where an increase was found in the levels of IL-1β and TNF in the retina." (PMID 25132733, 2014). "Glutamate, proteases, leukotrienes, IL-1β, IL-6, TNF-α, VEGF, lymphotoxin MMPs, and ROS have all been linked to diabetic retinopathy and a role for MIP-1, IL-1, and IL-3 in angiogenesis has been established in ischemic mouse models." (PMID 25258680, 2014). "Rodent models have demonstrated that the antioxidants that inhibit the development of diabetic retinopathy, also inhibit increases in retinal NF-kB and IL-1β." (PMID 24479616, 2014). "Interleukin converting enzyme/caspase-1, the enzyme responsible for the production of biological active IL-1β, is activated in the retina in both human and experimental diabetic retinopathy." (PMID 22615852, 2012). "Many molecular and cellular abnormalities detected in the diabetic retina support a role for IL-1β-driven neuroinflammation in the pathogenesis of diabetic retinopathy." (PMID 22615852, 2012). "Microglial-mediated release of TNF-α and IL-1β is a mechanism by which a pro-inflammatory environment exists in the diabetic retina and contributes to the development of experimental diabetic retinopathy." (PMID 22132311, 2011).
diabetic retinopathy (continued). "Additionally, in models of diabetic retinopathy, UA reduced inflammation (IL-6, IL-1β, TNF-α) and oxidative stress by increasing levels of SOD and GSH while decreasing MDA, effects associated with activation of the Nrf2/HO-1 pathway." (PMID 41374004, 2025). "Furthermore, IL-1β gene was markedly upregulated in the retinal vessels of diabetic retinopathy rats, and IL-1β protein levels were also elevated in the serum, vitreous fluid, and aqueous humor samples of diabetic retinopathy patients." (PMID 35576057, 2022). "Accordingly, the topical administration of d-MAPPSTM could result in the inhibition of TNF-α- and IL-1β-driven inflammation in retinal tissue and may be crucial in the prevention of diabetic retinopathy." (PMID 36362313, 2022). "In addition, and building on their in vitro observations, the team developed an in vivo model of diabetic retinopathy in which pro-inflammatory cytokines, IL1β and TNFα, were injected into the vitreous of NOD mice." (PMID 35054783, 2022). "Additionally, IL-1β accelerates the development of insulin resistance and neurovascular damage, both of which are very relevant in the development of diabetic retinopathy." (PMID 34281162, 2021). "The results of the current study also suggest that MGCs can play an important role in regulating the expression of pro-inflammatory cytokines such as IL-1β, ΙL-6, TNF-α, and IL-18 in the early stages of diabetic retinopathy, which was proposed to be associated with the inflammasome activation." (PMID 34071438, 2021). "In addition, not only were some of these differential response genes biologically relevant to diabetic retinopathy as exemplified by IL1B and PDGF, but also many had a genetic basis for their differential response." (PMID 33164750, 2020). "Many of those mediators have become research spots as they may stand as potential therapeutic targets for the treatment of diabetic retinopathy, IL-1β and TNF-α should be counted." (PMID 32019593, 2020). "It was pointed out that interrupting the IL-1β-induced autostimulation could limit the progression of diabetic retinopathy." (PMID 30057551, 2018). "Since overactivation of microglial cells may have deleterious effects in the retina, limiting IL-1β-mediated inflammatory processes could be a mechanism to prevent the progression of diabetic retinopathy." (PMID 28588350, 2017). "In conclusion, IL-1β might play a key role in diabetic retinopathy, affecting microglial and macroglial cells and ultimately contributing to neural changes observed in diabetic patients." (PMID 28588350, 2017). "Diabetic retinopathy also presents features of a low-grade chronic inflammatory disease, including increased levels of cytokines in the retina, such as interleukin-1 beta (IL-1β)." (PMID 28588350, 2017). "Interrupting the vicious circle triggered by IL-1β autostimulation could limit the progression of diabetic retinopathy." (PMID 22615852, 2012). "Intervention in the caspase-1/IL-1β/IL-1R1 feedback signaling by inhibition of caspase-1 as shown in this study or by the IL-1 receptor as we previously reported prevents Müller cell death in diabetic retinopathy demonstrating the importance of this signaling pathway to Müller cell viability." (PMID 39483336, 2024). "It has been also reported that IL-1β may have a role in the pathogenesis of diabetic retinopathy." (PMID 25518980, 2014). "Multiple cytokines and chemokines, such as IL-1β, IL-6, IL-8, TNF-α, and MCP-1, were found to be increased in serum and vitreous of the patients with diabetic retinopathy and DME." (PMID 40564027, 2025). "In diabetic retinopathy, the NLRP3 inhibitor verapamil can significantly inhibit TLR4-mediated NLRP3 activation, reduce IL-1β and TNF-α levels and improve RGC survival." (PMID 39736512, 2024). "Recent studies demonstrate that pro-inflammatory cytokines (IL-1b, IL-6, and TNF-α) in retinal tissues are involved in developing diabetic retinopathy." (PMID 37637673, 2023).
diabetic retinopathy (continued). "Literature was reviewed from common science libraries PubMed and Embase using various combinations of the search terms “diabetic retinopathy,” “HIF-1a,” “caspase-1,” and “IL-1B”." (PMID 37637673, 2023). "Elevated levels of pro-inflammatory cytokines such as IL-1β, TNF-α and IL-6 were found in the retinae of patients with diabetic retinopathy, as well as in mouse or rat models of diabetic retinopathy." (PMID 35309305, 2022). "Activated microglia and Müller cells release proinflammatory cytokines including IL-1β and TNF-α in diabetic retinopathy." (PMID 35010703, 2021). "This role for TXNIP in the development of diabetic retinopathy and nephropathy has been shown to be involved in NLRP3 inflammasome activation and release of IL-1β." (PMID 30733849, 2019). "Although there are a couple of drugs on the market that target the caspase-1/IL-1β complex none of them have been tested in the context of diabetic retinopathy." (PMID 39483336, 2024). "In addition, melatonin was shown to prevent the production of pro-inflammatory cytokines such as IL-1β and TNF-α in diabetic retinopathy." (PMID 35455066, 2022). "However, administration of folic acid downregulated inflammatory molecules (IL-1β and NLRP3) and oxidative markers in a mouse model of diabetic retinopathy." (PMID 34206804, 2021). "Folic acid (vitamin B9) may reduce inflammation (IL-1β and NLRP3) in a mouse model of diabetic retinopathy." (PMID 34206804, 2021). "This was one of the first reports demonstrating that IL-1β release from retinal pericytes exposed to high glucose is a P2X7R-dependent process, thus suggesting a novel potential pharmacological target for the treatment of diabetic retinopathy." (PMID 34281162, 2021). "Additionally, inflammatory cytokines (TNF-α, IL-1β, and IL-6) produced by CD68-expressing macrophages recruit inflammatory immune cells in the retinas of diabetic animals, crucially contributing to the development and progression of diabetic retinopathy." (PMID 36362313, 2022). "Pro- and active- forms of IL-1β have been found to be upregulated in the vitreous humor, aqueous humor, retina, and serum of patients with retinal degenerations such as wet AMD, diabetic macular edema, retinal detachment, RVO, glaucoma, retinitis pigmentosa, and diabetic retinopathy." (PMID 31379825, 2019). "Furthermore, in mice with STZ-induced diabetic retinopathy, intravitreal injection of the MC5R peptidomimetic agonist PG-901 attenuated, while MC5R antagonist PG20N augmented, retinal release of various inflammatory cytokines, such as IL-1α, IL-1β, IL-6, MIP-1α, MIP-2α, and MIP-3α." (PMID 35721571, 2022). "In addition, at the early stage of diabetic retinopathy, there is no significant increase in TNF-α or IL-1β levels compared to the CON group." (PMID 41317244, 2025). "Importantly, diabetic Cd40−/− mice are protected from retinal upregulation of intercellular adhesion molecule 1 (ICAM-1), TNF-α, IL-1β, nitric oxide synthase 2 (NOS2) and C-C motif chemokine ligand 2 (CCL2) and do not develop diabetic retinopathy." (PMID 35920844, 2022).
leukemia (68 papers, 2007 to 2026). A malignant (clonal) hematologic disorder, involving hematopoietic stem cells and characterized by the presence of primitive or atypical myeloid or lymphoid cells in the bone marrow and the blood. "Collectively, these data suggest that the effect of inflammasome mediated IL-1β secretion on leukemogenesis depends on the mutational context and can either favor or counteract leukemia." (PMID 35155452, 2021). "A previous study reported that Vegfa and Il1b transcripts are elevated in leukemia-associated macrophages in a NOTCH1-induced model of T-ALL54, suggesting secreted myeloid factors could promote FAK/PYK2 activation in T-ALL cells." (PMID 37805579, 2023). "Indeed, elevated IL-1β serum levels have been reported in patients with leukemia and are associated with poor prognosis." (PMID 32443460, 2020). "Our results also pointed out higher gingival fluid IL-1β values in children with leukemia compared to the control group." (PMID 41149097, 2025). "Shifting focus to IL‐1β, our results revealed high expression in four of six leukemia subtypes, with T‐ALL and ETP‐ALL harboring the lowest expression." (PMID 40104043, 2025). "In our study, IL-1β values in gingival crevicular fluid of children with leukemia and gingival alterations were significantly higher with respect to the control group." (PMID 41149097, 2025). "In our study, we found raised expression of IL-6, IL-17α, and TGF-β1 values both in the plasma and GCF of children with leukemia as compared to healthy subjects, while the levels of IL-1β were elevated only in the GCF." (PMID 41149097, 2025). "Several studies have reported a correlation between dysregulated IL-1β secretion and leukemia progression and poor prognosis." (PMID 38903927, 2024). "Targeted inhibition of the IκB kinase complex reduced IL‐1β responses and induced cell death in primary IDH‐mutated leukemia samples." (PMID 39157630, 2024). "Since IL-1β is one of the main components of inflammasomes involved in pathogenesis in leukemias, the study of genetics can contribute to the discovery of new biomarkers that can predict clinical parameters in the disease." (PMID 37577033, 2023). "Downregulation of HIF1α, oxidative phosphorylation, and PI3kinase pathways at EOI along with the regulators IFNG, TNF, VEGFA, IL1B in B cells is likely to impede leukemia supportive pro-inflammatory signaling." (PMID 37532715, 2023). "IL‐1β signalling promotes the expansion of leukaemia cells while suppressing normal myeloid progenitors." (PMID 36124714, 2022). "In an MLL-AF9-driven leukemic mouse model, chronic exposure to IL-1β accelerated leukemia progression and impaired normal hematopoiesis by modulating stromal niche support." (PMID 36248849, 2022). "Treatment of human leukemia THP-1 cells with BF-induced inflammatory cytokine interleukin-1 beta (IL-1β) and tumor necrosis factor-α (TNF-α)." (PMID 36235123, 2022). "IL‐1β is a proinflammatory factor that has been described as hyperexpressed in various types of solid cancers as well as leukaemia." (PMID 36124714, 2022). "Our results showed that caspase-1 inhibitor Z-YVAD-FMK down-regulated IL-1β and IL-18 secretion, suppressed proliferation and enhanced apoptosis of primary leukemia cells." (PMID 34211462, 2021). "Knocking down endogenous IL-1β or anti-IL-1β antibody inhibits leukemia cells whereas IL-1β cytokine enhances leukemia proliferation." (PMID 34211462, 2021). "Several studies have shown that dysregulated IL-1β secretion and/or signaling in leukemia, especially AML, ALL and CML, positively correlates with disease progression and poor prognosis." (PMID 33525345, 2021). "Since leukemia is known to be an inflammation-driven cancer and IL-1β is produced in elevated levels by leukemic cells, research on NLRP3 in the context of leukemia has increased in recent years." (PMID 33525345, 2021).